CDK1 (cyclin dependent kinase 1)
Diseases named in the same sentence as CDK1 in open-access papers (continued):
Sharing a sentence is not in itself a finding about the gene and the disease.
cystitis (1 paper, 2021). Inflammation of the urinary bladder. "Moreover, the experimental results of real‐time PCR and Western blot analysis analysis demonstrated that the expression of Cdk1 at the mRNA and protein levels in cystitis tissues was significantly increased in different animal models of chemical cystitis compared with the control group." (PMID 34080795, 2021).
dementia (1 paper, 2022). Loss of intellectual abilities interfering with an individual's social and occupational functions. "Upon validation using postmortem human brain samples, CDK1 tended to be upregulated in individuals with HIV-associated dementia in comparison to the normal control." (PMID 36560797, 2022). "Upon the analysis of the GSE35864 data set, the results indicate that Cdk1 was upregulated in HIV-associated dementia in comparison to the normal control." (PMID 36560797, 2022). "This analysis proved that CDK1 is upregulated in the HIV-associated dementia group (which is linked with the expression of gp120 protein) compared to the normal control." (PMID 36560797, 2022).
Dengue virus infection (1 paper, 2025). "Key regulatory genes such as AURKA, BUB1, BUB3, and CDK1 are found to be involved in cell cycle regulation and have roles in immune-related pathways, underscoring their importance in the host immune response to Dengue virus infection." (PMID 40100920, 2025).
diabetic nephropathy (1 paper, 2024). "This indicates that in the treatment of diabetic nephropathy, CDK1 is anticipated to be a key target for controlling the cell cycle and reducing the loss of glomerular podocytes and associated fibrosis." (PMID 39830349, 2024). "It was also shown that FGF21 dramatically reduces the expression of CDK1, which may help diabetic nephropathy by averting mitotic catastrophe and changing the renal cell cycle." (PMID 39830349, 2024). "In short, FGF21 improved the development of diabetic nephropathy in diabetic nephropathy-affected animals by reducing glomerular filtration damage, inflammation, and oxidative stress, inhibiting the formation of thrombus, and controlling the cell cycle through CDK1." (PMID 39830349, 2024). "This indicates that via regulating CDK1 to regulate the cell cycle in renal tissues, FGF21 is likely to slow down the mitotic catastrophe and, consequently, the progression of diabetic nephropathy." (PMID 39830349, 2024).
Ductal carcinoma in situ (1 paper, 2017). "We thus concluded that Five genes: CDK1, CCNB2, MAD2L1, PPARG, ACACB were finally identified to participate in the regulation and serve as potential diagnosis signatures in in Ductal carcinoma in situ." (PMID 28977921, 2017).
endometrial tumors (1 paper, 2020). "In addition, pathway analysis and clustering of the endometrial tumors in the TCGA data set revealed that dysregulation of mitotic processes is a frequent occurrence in USC, including increase in cyclin B1, CDK1 and cyclin E1 protein expression." (PMID 31906456, 2020).
experimental autoimmune encephalomyelitis (1 paper, 2016). An autoimmune demyelinating disease of the central nervous system that is produced experimentally in animals by the injection of homogenized brain or spinal cord in Freund's adjuvant. "In this line, their results showed that CDK (including CDK1) inhibitors prohibited Th17 differentiation and expedited iTreg (induced regulatory T cells) development, which induced improving of experimental autoimmune encephalomyelitis in mice." (PMID 28028462, 2016).
fibrosis (1 paper, 2025). the formation of excess fibrous connective tissue in an organ or tissue in a reparative or reactive process. "The potential of CDK1 as a therapeutic biomarker for liver fibrosis and HCC should be further exploited and validated in future studies." (PMID 40332418, 2025).
Focal cortical dysplasia (1 paper, 2019). A type of malformation of cortical development that primarily affects areas of neocortex. "Glioneuronal lesions caused by focal cortical dysplasias (FCDs), which are frequently encountered in biopsy specimens of patients with pharmacoresistant focal epilepsy, may be related to the impaired expression of CDK1 in FCD." (PMID 31427480, 2019).
gastric MALT lymphoma (1 paper, 2012). "Since CDK1 activation is associated with the cell proliferation in developing gastric MALT lymphoma." (PMID 22970268, 2012).
gastritis (1 paper, 2012). Inflammation of the stomach. "A recent study revealed that increased expression of CDK1 is associated with the progression from H. pylori-associated gastritis to mucosa-associated lymphoid tissue lymphoma." (PMID 22970268, 2012).
glaucoma (1 paper, 2023). Increased pressure in the eyeball due to obstruction of the outflow of aqueous humor. "We found that Cdk1 (cyclin-dependent kinase 1) was increased in UON and MON ON crush and glaucoma tissues at three days, though cyclin D1 (Ccnd1), its downstream target was not." (PMID 37762022, 2023).
Glucose intolerance (1 paper, 2023). Glucose intolerance (GI) can be defined as dysglycemia that comprises both prediabetes and diabetes. "Taken together, our findings lend support to studies showing that glucose intolerance in mice may be related to the phosphorylation status of 4E-BP1, particularly at 4E-BP1 residue S82, a residue that is phosphorylated by CDK1 but not mTOR." (PMID 36897840, 2023).
Graves disease (1 paper, 2011). Graves' disease is an autoimmune disorder that leads to overactivity of the thyroid gland (hyperthyroidism).It is caused by an abnormal immune system response that causes the thyroid gland to produce too much thyroid hormones. "Here we show that an additional factor, gene expression of Cdk1 in mononuclear cells, is positively related to concentrations of TRAb in patients with untreated Graves' disease." (PMID 22363873, 2011). "The main finding in the present study is, however, the significant decrease in Cdk1 mRNA in treated patients with Graves' disease as compared with the other two groups." (PMID 22363873, 2011). "Multiple regression analysis was performed in untreated patients with Graves' disease with log TRAb as the dependent variable and Heg RNA amol/μg DNA and log Cdk1 mRNA zmol/μg DNA as independent variables." (PMID 22363873, 2011). "In patients with untreated Graves' disease, multiple regression analysis with Heg RNA and Cdk1 mRNA as independent variables showed that Cdk1 mRNA values were positively related to TRAB." (PMID 22363873, 2011). "The decrease in CDk1 mRNA and in TRAb is likely to be a specific effect of antithyroid drug treatments, and at present it is unclear if this effect is seen only in patients with Graves' disease." (PMID 22363873, 2011).
heart failure (1 paper, 2022). Inability of the heart to pump blood at an adequate rate to meet tissue metabolic requirements. "In addition, CDK1 regulates the cell cycle leading to cell cycle arrest in cardiomyocytes, the latter being an important factor involved in oxidative stress leading to heart failure." (PMID 35749386, 2022).
Hypertension (1 paper, 2025). The presence of chronic increased pressure in the systemic arterial system. "BUB1B and CDK1, key regulators of mitosis and cell cycle progression, likely reflect proliferative vascular responses and endothelial turnover in hypertension." (PMID 40909129, 2025).
Hypoglycemia (1 paper, 2023). A decreased concentration of glucose in the blood. "The purpose of this docking was to investigate whether the primary bioactive constituents of the compound played a role in hypoglycemia through the compound's key targets, which were CDK2, E2F1, CDKN1A, CDK1, and CCND1 and CCNB1." (PMID 36846049, 2023).
hypothyroidism (1 paper, 2024). Abnormally low levels of thyroid hormone. "The relative expression of three cell cycle promoters (CDK1, CDK2, and CDK4), and one cell cycle inhibitor (CDKN1A) was compared in each tissue to determine the effect of hypothyroidism on the developing fetus." (PMID 38902754, 2024).
injury (1 paper, 2025). Damage inflicted on the body as the direct or indirect result of an external force, with or without disruption of structural continuity. "Despite these limitations, this study provides new molecular biomarkers for early AKI diagnosis in gastrointestinal cancer patients, particularly CDK1 and STAT1, whose combined detection shows potential for early kidney injury assessment and offers a solid foundation for clinical application." (PMID 39911265, 2025).
invasive ductal carcinoma (1 paper, 2024). "By shedding light on the interplay between CDK1 and DTL expression, our findings contribute to understanding the regulatory landscape of invasive ductal carcinoma and pave the way for future investigations and novel therapeutic avenues." (PMID 39567714, 2024).
ischemia (1 paper, 2018). A hypoperfusion of the BLOOD through an organ or tissue caused by a PATHOLOGIC CONSTRICTION or obstruction of its BLOOD VESSELS, or an absence of BLOOD CIRCULATION. "In this study, we used both genetic and pharmacological approaches to investigate the role of Cdk1 following ischemia." (PMID 29581894, 2018).
large cell lymphomas (1 paper, 2023). "Clusters 3.4 and 3.6 also featured upregulation of genes implicated in large cell lymphomas, and notably overlapping with several genes enriched in RT tumors compared to matched CLL precursors, including Birc5, Cdk1, Mki67, and Npm1." (PMID 36609611, 2023).
laryngeal tumors (1 paper, 2016). "The in-depth analysis of our microarray expression profiles showed higher CDK1 expression in both larynx cancer cell lines and primary tumor samples in comparison to normal controls." (PMID 26912061, 2016).
latent infection (1 paper, 2023). "The cell proliferation marker MKI67 as well as genes involved in G1-S and G2-M transition, such as CDK1, CDK2, CCNE2, PRIM2, AKT1, and FOXM1, were significantly downregulated in latent infection compared to actively infected cells." (PMID 38038477, 2023).
leishmaniasis (1 paper, 2014). Infectious disease that is transmitted through the bite of hematophagous female phlebotomine sand flies. "The Cyclin-Dependent Kinase1 (CDK1) homologue of Leishmania [cdc2-related protein kinase 3 (LCRK3)] and the glycogen synthase kinase-3short (LGSK-3) have emerged amongst other kinases as putative molecular drug targets for the treatment of leishmaniasis." (PMID 24886176, 2014).
lumbar disc degeneration (1 paper, 2025). "Analysis of the training set revealed that the expression levels of the cell cycle regulatory gene CDK1 and the extracellular matrix gene COL4A2 were significantly elevated in patients with lumbar disc degeneration compared to controls." (PMID 41409278, 2025).
male infertility (1 paper, 2022). The inability of the male to effect fertilization of an ovum after a specified period of unprotected intercourse. "Previous studies demonstrated that CDK1, a known cell cycle regulator, is required for completion of metaphase progression in spermatocytes, and its loss of function can result in meiotic arrest and male infertility." (PMID 35909681, 2022).
malignant glioma (1 paper, 2025). A grade III or grade IV glioma arising from the central nervous system. "Conversely, silencing KAT8 in malignant glioma cells downregulated cyclin-dependent kinase 1 (CDK1), cyclin A, and cyclin B expression and upregulated p21 expression, leading to G2/M-phase arrest." (PMID 40508066, 2025).
memory impairment (1 paper, 2021). "A previous result showed that Cyclin B2 and CDK1 increased in the condition of neurodegeneration and memory impairment." (PMID 34561612, 2021).
metastasis (1 paper, 2020). The spread or migration of cancer cells from one part of the body (where they first appeared) to another. "In addition, we did not analyze the expression of hub genes, such as CDK1, in pancreatic patients with or without lymphatic metastasis or use ROC analysis to explain the prognosis and diagnostic value of the genes." (PMID 32587798, 2020).
myeloid leukemia (1 paper, 2019). A clonal proliferation of myeloid cells and their precursors in the bone marrow, peripheral blood, and spleen. "Finally, the Myc-Cdk1-p27 axis is not only operative in mouse fibroblasts but also confirmed in human myeloid leukemia cells with conditional expression of Myc and p27." (PMID 31822694, 2019).
myoma (1 paper, 2021). "It has also been reported that vitamin D inhibits uterine myoma cell growth through the downregulation of proliferating cell nuclear antigen and cyclin-dependent kinase 1 and the inhibition of COMT expression and activity." (PMID 33504114, 2021).
nasal natural killer/T-cell lymphoma (1 paper, 2023). "CDK1 expression was up-regulated in EBV-positive DLBCL and nasal natural killer/T-cell lymphoma (NNKTL)." (PMID 37072474, 2023).
neuro-degenerative diseases (1 paper, 2026). "We discuss how key regulators of this transition-including Cdk1, centrosomal γ-tubulin recruitment, Golgi-derived microtubule nucleation, and the kinase MARK4 may constitute druggable nodes to tune microglial reactivity in neuro-degenerative diseases." (PMID 42088827, 2026).
neuropathy (1 paper, 2024). A disorder affecting the nervous system that manifests with pain, tingling, numbness, and/or muscle weakness. "Specific genes increased in patients withoutlinezolid-associated neuropathy included ATG4C, BAX, and IGF1, while patients onlinezolid who suffered from neuropathy had an increase in AURKB, CASP3, CASP8, CDK1,CDKN1B, CEBPB, NADSYN1, NRF1, GPX7, and SBSN." (PMID 38939039, 2024).
odontogenic tumors (1 paper, 2016).
osteonecrosis of (1 paper, 2023). "The Venn diagrams showed six intersecting genes related to osteonecrosis of the femoral head, OS and APO targets: NFE2L2 (Nrf2), ERN1, PDGFRB, PDGFRA, KEAP1 and CDK1." (PMID 37749949, 2023).
Ovarian cyst (1 paper, 2021). The presence of one or more cysts of the ovary. "Our result indicated that Jingshu granules may exert a medicinal effect by targeting the MAPK8 and CDK1 of the progesterone-mediated oocyte maturation signaling pathway in ovarian cysts." (PMID 33623786, 2021).
overnutrition (1 paper, 2019). An imbalanced nutritional status resulting from excessive intake of nutrients. "Epigenetic regulation of Cdk1 has not previously been implicated in a hepatic response to overnutrition and increased adiposity." (PMID 31920990, 2019).
pancreatitis (1 paper, 2024). Inflammation of the pancreas. "HTRA1 is high expressed in PDAC, and severs as a critical activator for tumor cells malignant phenotype and pancreatitis-initiated PDAC progression by targeting CDK1-mediated cell cycle." (PMID 38287020, 2024). "Mechanistically, HTRA1 interacted with CDK1 protein, and CDK1 inhibitor reversed the malignant phenotype of PANC-1 and pancreatitis-initiated PDAC activated by HTRA1 overexpression." (PMID 38287020, 2024).
pneumonitis (1 paper, 2019). An inflammatory process affecting the lung parenchyma. "SNP rs10711, located in the 3′UTR region of CDK1 (encoding for cyclin-dependent kinase 1) was significantly associated with a higher risk of pneumonitis (OR = 2.67, 95% CI = 1.26–5.63, P = 0.010)." (PMID 31555602, 2019).
primary effusion lymphoma (1 paper, 2023). A large B-cell lymphoma located in the body cavities, characterized by pleural, peritoneal, and pericardial fluid lymphomatous effusions and that is always associated with human herpes virus-8 (HHV-8). "Treating the primary effusion lymphoma (PEL) cells with iMDK resulted in strong induction of cell cycle arrest in the G2/M phase and led to the reduction of p-CDK1 protein level." (PMID 37240085, 2023).
Primary Immunodeficiency (1 paper, 2025).
retinal degeneration (1 paper, 2022). Degeneration of the retina. "All in all, our study suggests that CDK1 has functions during retinal degeneration, and in particular, in the late stages of photoreceptor death." (PMID 35883586, 2022). "A previous study demonstrated the expression of cell cycle proteins, such as cyclin dependent kinase 2 and cyclin dependent kinase 4, in rd1, but details of CDK1 expression during retinal degeneration have, to our knowledge, not been reported." (PMID 35883586, 2022).
retinitis pigmentosa (1 paper, 2022). Retinitis pigmentosa (RP) is an inherited retinal dystrophy leading to progressive loss of the photoreceptors and retinal pigment epithelium and resulting in blindness usually after several decades. "However, the details of if and how CDK1 might be involved in the neurodegenerative condition, retinitis pigmentosa (RP), which displays progressive vision loss, are unclear." (PMID 35883586, 2022).
salivary gland tumor (1 paper, 2019). "Unlike BPTES, which causes cell cycle arrest at the S and/or G2 phase, our previous study showed that metformin could induce cell cycle arrest of salivary gland tumor cells in the S and G2 phases via inhibition of cyclin dependent kinase 1 and cyclin B40." (PMID 30899051, 2019).
scleroderma (1 paper, 2025). Scleroderma is a rare autoimmune connective tissue disorder characterized by abnormal hardening of the skin and, sometimes, other organs. "In conclusion, our study provides new evidence that esomeprazole exerts anti-proliferative effects on scleroderma fibroblasts by inducing cell cycle arrest through p21 upregulation and CDK1 and CDK2 downregulation." (PMID 41567630, 2025).
Sepsis (1 paper, 2024). Sepsis is defined as life-threatening organ dysfunction caused by a dysregulated host response to infection. "Interestingly, CDK1 expression has previously been associated with mortality in sepsis, albeit in one unique report." (PMID 39830374, 2024). "Finally, the CDK1/CX3CR1 ratio can be used in combination with lactate levels for prognostic and predictive enrichment in sepsis patients." (PMID 39830374, 2024).
steatosis (1 paper, 2020). Increased lipid within the cytoplasm of cells. "This would then lead to a net accumulation of lipids that caused the manifestation of steatosis, resulting in an inversion of the lipid phenotype in the liver of Cdk1 cKO mice upon aging." (PMID 33345777, 2020). "Thus, we investigated whether steatosis had developed in the liver of aged Cdk1 cKO mice." (PMID 33345777, 2020).
thymic atrophy (1 paper, 2026). "Collectively, these results suggest that ADX-induced elevation of estrogen hormones accelerated age-related thymic atrophy in females, likely by promoting Pparg-dependent adipogenesis and blocking Cdk1-dependent thymocyte cell cycle progression." (PMID 41596668, 2026).
tongue cancer (1 paper, 2021). A malignant neoplasm affecting the tongue. "A high level of CDK1 expression was positively associated with tumor grades of tongue cancer and negatively correlated with the survival time." (PMID 34440557, 2021).
tongue tumors (1 paper, 2024). "Previous studies suggest that CDK1, CCNA2, and CCNB1 may be associated with inflammation, immune system disorders, and tongue tumors." (PMID 39553152, 2024).